AFP (alpha fetoprotein)
Diseases named in the same sentence as AFP in open-access papers (continued):
Sharing a sentence is not in itself a finding about the gene and the disease.
testicular tumors (34 papers, 2009 to 2026). "Measurement of AFP levels and ultrasonography are important diagnostic tools for testicular tumors before surgery." (PMID 36795187, 2023). "It is the most common testis tumor in children younger than 2 years of age, presenting as a solid testicular mass associated to increased levels of AFP." (PMID 24400293, 2013). "The patient presented with a left scrotal mass, markedly elevated serum alpha-fetoprotein and human chorionic gonadotropin levels, and ultrasonographic findings suggestive of a testicular tumor." (PMID 41924289, 2026). "Given the high clinical suspicion of a testicular tumor, serum tumor markers, including alpha-fetoprotein, human chorionic gonadotropin (hCG), and lactate dehydrogenase (LDH), were assessed and found to be within normal limits." (PMID 41306546, 2025). "Mostly, diagnosis of testicular tumors begins with evaluating tumor markers such as alpha-fetoprotein (AFP), beta-subunit of human chorionic gonadotropin (B-hCG), and lactate dehydrogenase (LDH)." (PMID 38817519, 2024). "Diagnosis of testicular tumors begins with assessing tumor markers such as AFP, B-hCG, and lactate dehydrogenase (LDH)." (PMID 38817519, 2024). "Tumors, including testicular tumors (germ cell, Sertoli or Leydig cell tumor) and extragonadal tumors, were excluded by testicular ultrasound and normal hCG, β-hCG and AFP levels in laboratory exams." (PMID 39634186, 2024). "Tumor markers were significantly elevated, with AFP at 19,420 ng/mL and HCG at 4,749 mIU/mL, indicating a high-risk testicular tumor." (PMID 39697937, 2024). "Testicular tumours and EGGCTs also share similar serological features, such as secretion of the tumour markers alpha-fetoprotein (AFP) and beta-human chorionic gonadotropin (β-HCG)." (PMID 39518633, 2024). "Our results concur with these findings; we recognized asymptomatic scrotal conditions and elevated serum AFP or β-HCG levels as standalone predictors of testicular tumors." (PMID 38240867, 2024). "The main methods for diagnosis of testicular tumors are physical examination, radiography, ultrasound and biochemical tumors markers including alpha-fetoprotein (AFP), human chorionic gonadotropin (HCG) and lactate dehydrogenase (LDH)." (PMID 36185298, 2022). "Testicular tumor markers are a major tool in evaluating pediatric testicular tumors; these include alpha-fetoprotein (AFP) and beta-human chorionic gonadotrophin (BHCG)." (PMID 35804952, 2022). "Tumour markers (human chorionic gonadotropin and alpha-fetoprotein) were available for 42 patients (38 with complete regression of the testicular tumours and 4 with partial regression)." (PMID 36011006, 2022). "In prepubertal testicular tumors the focus lies on AFP reflecting the YST component, whereas malignant prepubertal tumors that produce hCG are rarely found." (PMID 33036134, 2020). "Based on these findings, a presumptive diagnosis of testicular tumor was made, prompting the evaluation of serum tumor markers, which revealed significantly elevated alpha-fetoprotein (AFP), lactate dehydrogenase (LDH), and beta-human chorionic gonadotropin (β-hCG) levels." (PMID 40429559, 2025). "Therefore, preoperative assessment, including scrotal US, AFP level, and CT evaluations, is crucial in the diagnosis of pediatric testicular tumors, as the results play a significant role in guiding the choice of surgical procedure." (PMID 41255769, 2025). "In children younger than 1 year with testicular tumors, an elevated AFP level may also be observed in those with benign tumors." (PMID 39606696, 2024). "Furthermore, certain serum markers associated with testicular tumours – LDH (lactate dehydrogenase), AFP (alpha-fetoprotein), HCG (human chorionic gonadotropin), and ACE (angiotensin-converting enzyme) – are evaluated in the laboratory." (PMID 38090555, 2023).
testicular tumors (continued). "Therefore, for children < 1 year old with testicular tumors, AFP level may be elevated in those with benign tumors, whereas for children > 1 year, a normal AFP level often indicates a benign tumor." (PMID 35804952, 2022). "In testicular tumors, combining hCG with other similar markers, such as alpha-fetoprotein (AFP), could improve the efficacy of the measurement; however, assessment of hCG and AFP is generally not recommended in NETs, since both lack the sensitivity of specificity of CgA." (PMID 31382663, 2019). "Therefore, for children <1 year old with testicular tumors, an elevated AFP level could be detected in those with benign tumors." (PMID 28347316, 2017). "The testicular tumor markers were within normal range: lactate dehydrogenase (LDH) 150 units/L, alpha-fetoprotein (AFP) 12 ng/mL, and beta-human chorionic gonadotrophin (β-HCG) less than 2 mIU/mL." (PMID 34544483, 2021). "Alpha-feto-protein (AFP) is an important tumor marker, and has increased blood levels in most cases of malignant prepuberal testicular tumors." (PMID 24400293, 2013). "Tumor markers like AFP and β-HCG are instrumental in pinpointing testicular tumors." (PMID 38240867, 2024). "Studies have shown that AFP and HCG have certain values in the diagnosis of testicular tumor types." (PMID 36550425, 2022). "The common testicular tumor markers LDH, AFP and hCG are typically normal in SCSTs." (PMID 24044431, 2013). "In our practice we use to determine serum AFP and B-HCG in all infants with a testicular tumors." (PMID 23217189, 2012). "Classically, nonseminoma testicular tumors are known to secrete AFP." (PMID 37485120, 2023). "Also, serum tumor markers such as AFP and β-hCG are not helpful in distinguishing primary from secondary testicular tumors." (PMID 26066034, 2015). "Most studies report elevated AFP concentrations in approximately 70% of patients with HCC and in 50% to 70% of patients with nonseminomatous testicular tumors." (PMID 34746648, 2021). "Concerning the majority of SE tumors that do not contain a syncytiotrophoblastic component (~80%), diagnosis and follow-up based on the evaluation of only AFP and LDH serum levels are not sufficient, as they are generally not elevated in this kind of testicular tumor type." (PMID 40723290, 2025).
Ataxia (33 papers, 2009 to 2026). Ataxia refers to impaired coordination of voluntary muscle movement. "Cerebellar ataxia is the main clinical feature of Classical AT, often with telangiectasia, immune deficiency, and increased alpha-fetoprotein (AFP) levels." (PMID 35586824, 2022). "In our survey ~60% of juvenile-to-adult cases with cerebellar ataxia, sensorimotor neuropathy and increased AFP are due to mutations in the SETX gene, and a smaller percentage to APTX and ATM gene mutations." (PMID 23941260, 2013). "The ESID diagnostic criteria for AT includes ataxia and at least two of the following features: (a) oculo-cutaneous telangiectasia, (b) elevated alpha-fetoprotein (AFP), (c) typical AT karyotype (translocation of chromosomes 7; 14), (d) cerebellum hypoplasia on MRI." (PMID 31921190, 2019). "This autosomal recessive complex disorder with substantial severity in affected individuals is characterized by ataxia, ocular and cutaneous telengiectasia, radiosensitivity, immunodeficiency, increased predisposition to malignancies and elevated serum alpha fetoprotein level." (PMID 30026765, 2018). "However, the second reported patient featured ataxia, telangiectasia, elevated AFP, IgA deficiency, microcephaly, and pulmonary failure." (PMID 29255463, 2017). "AFP is a biomarker for neurodegenerative diseases (like cerebellar ataxia), and is considered to potentially promote repair after neural injury by regulating neurogenesis‐related signalling pathways." (PMID 40511628, 2026). "This Chinese girl presented with growth retardation, ataxia, medium ocular telangiectasia, cerebellar atrophy, elevated serum alpha-fetoprotein (AFP) level, and normal serum levels of immunoglobulins, which are all similar to our proband." (PMID 38882696, 2024). "Oculomotor apraxia type 2 (AOA2), an autosomal recessive spinocerebellar ataxia, with adolescent or early adult onset progressive ataxia, oculomotor apraxia, neuropathy, cerebellar atrophy, and elevated alpha-fetoprotein levels." (PMID 37008993, 2023). "Clinical features of the two siblings were teenage onset of ataxia, axonal polyneuropathy, reduced deep tendon reflexes, normal cognitive function, and elevated levels of AFP." (PMID 35203940, 2022). "All diagnosed patients either based on clinical criteria or with a confirmed molecular diagnosis had characteristic features of ataxia, ocular telangiectasia, and increased levels of alpha fetoprotein." (PMID 35260754, 2022). "The literature review showed that ataxia, polyneuropathy, and elevated AFP are common features and OMA is a variable sign of AOA2 from different populations, whereas OMA is rare and saccadic pursuit and nystagmus are common in East Asian AOA2." (PMID 35203940, 2022). "The literature review shows that ataxia, polyneuropathy, and elevated AFP are common features and ocular motor apraxia (OMA) is a variable sign of AOA2 from different populations." (PMID 35203940, 2022). "We identified three Iranian AT patients (3/249, 1.2% of total registry) with later age at ataxia onset and slower neurologic progression despite elevated alpha-fetoprotein levels, history of respiratory infections, and immunological features of the syndrome." (PMID 35095854, 2022). "Blood tests including alpha‐fetoprotein, albumin, cholesterol, lactate/pyruvate, and cytosine‐thymine‐guanine repeats in spinocerebellar ataxia 1, 2, 3, and dentatorubral pallidoluysian atrophy disclosed no abnormalities in both patients." (PMID 32895939, 2021). "This renders the distinction of AT from AOA1 and AOA2 more difficult while further supporting their inclusion into the recessive ataxias with complex oculomotor disturbances and elevated AFP group." (PMID 29127364, 2017). "Our findings are that AOA1, AOA2 and AT form a particular group characterized by ataxia with complex oculomotor disturbances and elevated AFP for which the final diagnosis is relying on genetic analysis." (PMID 29127364, 2017).
Ataxia (continued). "AOA1, AOA2 and AT should be considered among ARCAs as a particular group of ataxia with complex oculomotor disturbances and elevated AFP for which the diagnosis relies on genetic analysis." (PMID 29127364, 2017). "For these cases with early onset of ataxia, oculomotor impairment, and recessive history, it is necessary to inspect serum AFP and make EMG test." (PMID 27644330, 2016). "Taken together, these were in line with the features of AOA2, which was characterized by juvenile-onset cerebellar ataxia, oculomotor apraxia, sensorimotor neuropathy, marked cerebellar atrophy, and elevated serum AFP." (PMID 27644330, 2016). "All A-T patients (CHATs) had the typical symptoms of ataxia and telangiectasia, sign of cerebellar atrophy by CT and MRI examinations, and elevated serum alpha-fetoprotein." (PMID 23807571, 2013). "We describe the clinic and molecular study of a large series of 22 Italian patients (21 families) selected for having cerebellar ataxia, peripheral neuropathy and elevated alpha-fetoprotein serum level." (PMID 23941260, 2013). "In this study, we performed a mutational screening of ATM, APTX, SETX in a selected cohort of twenty-two Italian patients presenting cerebellar ataxia, sensorimotor axonal neuropathy, and elevated AFP." (PMID 23941260, 2013). "The gait instability suggestive of cerebellar ataxia prompted us to the diagnosis of AT which was further supported by the simultaneous increase in alpha-fetoprotein (13 ng/mL)." (PMID 25374739, 2013). "This autosomal recessive, slowly progressing ataxia is characterized by cerebellar symptoms, oculomotor apraxia, elevated serum alpha-fetoprotein (AFP) levels, and peripheral neuropathy." (PMID 23015802, 2012). "By age 3 years, she had progressively worsening ataxia, choreoathetosis, prominent ocular telangiectasias and an elevated alpha fetoprotein of 205.4 ng/mL (normal 0–6 ng/mL) consistent with ataxia-telangiectasia." (PMID 19284625, 2009). "It is worthy to note that, in some cases of AOA2, the AFP levels may be normal initially; therefore, AFP levels assessments should be repeated during the course of an ataxia of unknown etiology." (PMID 35203940, 2022). "Ataxia with oculomotor apraxia type 2 (AOA2)/autosomal recessive spinocerebellar ataxia with axonal neuropathy-2 (SCAN2) (OMIM #606002) is characterized by early-onset progressive cerebellar ataxia, polyneuropathy, and elevated levels of alpha-fetoprotein (AFP)." (PMID 35203940, 2022). "Elevated AFP serum levels are also found in ataxia with ocular apraxia types 2 and 4 (AOA2, AOA4)." (PMID 33779842, 2021). "Our findings broaden the spectrum of ataxia with elevated AFP and will help reverse-phenotyping in cases of first genotyping and in the interpretation of the numerous variants of unknown significance provided by premature NGS." (PMID 29127364, 2017). "Patients with typical AT, the second most frequent recessive ataxia after Friedreich ataxia (FRDA), have progressive cerebellar ataxia in early childhood, typical OMA, oculo-cutaneous telangiectasia, immunodeficiency inducing recurrent infections, increased cancer risk and elevated AFP serum level." (PMID 29127364, 2017). "In conclusion, we suggest that patients with ataxia, neuropathy and elevated alpha-fetoprotein should be screened for SETX and ATM genes, given that an overlapping phenotype may be present among these different genetic defined entities." (PMID 23941260, 2013). "Ataxia with oculomotor apraxia type 2 (AOA2) is characterized by onset of ataxia between age 10 and 25 years, sensorimotor neuropathy, postural tremor, dystonia, strabismus, oculomotor apraxia, cerebellar atrophy and elevated serum level of alpha-fetoprotein (AFP)." (PMID 35745683, 2022). "Therefore, if initially normal, AFP assessments should be repeated during the evolution of an ataxia of unknown etiology." (PMID 29127364, 2017).
Ataxia (continued). "AOA2 patients develop cerebellar ataxia in the second decade of life, sensorimotor neuropathy, occasional OMA, strabismus, chorea, dystonia and elevated alpha-fetoprotein (AFP) serum levels." (PMID 29127364, 2017). "Our patient presented with cerebellar ataxia, polyneuropathy, generalized areflexia, saccadic pursuit, slow saccadic eye movements without oculomotor apraxia (OMA), chorea, and elevated levels of AFP." (PMID 35203940, 2022). "Whether the recessive ataxias, Ataxia with oculomotor apraxia type 1 (AOA1) and 2 (AOA2) and Ataxia telangiectasia (AT), can be distinguished by video-oculography and alpha-fetoprotein level remains unknown." (PMID 29127364, 2017). "All cases from Eastern Asian had cerebellar ataxia and polyneuropathy and their age of onset were all within the second decades and 91% of them had elevated AFP, which is similar to series cases reported from Europe, North Africa, North America, and the Middle East." (PMID 35203940, 2022). "Therefore, in patients with undiagnosed dystonia, AT should be considered, screening for AFP may help in diagnosis, and even in the absence of ataxia symptoms, the possibility of AT should be considered." (PMID 35586824, 2022). "In FRDA, ataxia typically appears between 10 and 15 years of age, and differs from A-T by the absence of telangiectasia and oculomotor apraxia, the early absence of tendon reflexes, a normal AFP, the frequent presence of scoliosis, and abnormal features on the EKG." (PMID 27884168, 2016). "AFP serum levels in ataxic patients were significantly increased in the AOA1, AOA2 and AT groups relative to those in 100 control patients without cerebellar ataxia." (PMID 29127364, 2017).
anemia (32 papers, 2010 to 2026). A reduction in the number of red blood cells, the amount of hemoglobin, and/or the volume of packed red blood cells. "Laboratory workup demonstrated severe iron-deficiency anemia, low albumin, and normal serum alpha-fetoprotein (AFP) and beta-hCG." (PMID 31118058, 2019). "Laboratory testing revealed mild anaemia with leukocytosis and thrombocytosis, markedly elevated carcinoembryonic antigen and normal alpha-fetoprotein." (PMID 42100591, 2026). "Patient responded well to treatment; his anemia gradually improved, and alpha-fetoprotein levels significantly declined." (PMID 40686768, 2025). "Laboratory tests showed anemia, hypoalbuminemia, and elevated AFP, and imaging revealed a large hepatic mass with necrosis." (PMID 40842593, 2025). "Laboratory tests indicated severe anemia (hemoglobin: 57 g/L), while tumor markers, including alpha-fetoprotein (AFP), carcinoembryonic antigen (CEA), carbohydrate antigen 199 (CA199), and carbohydrate antigen 724 (CA724), were within normal ranges." (PMID 41141698, 2025). "The most common clinical characteristics were abnormal clotting times (62.5%), elevated alpha fetoprotein (37.5%), anemia (31.3%), and metabolic acidosis (31.3%)." (PMID 39311361, 2024). "The most common clinical characteristics reported in the charts were abnormal clotting times based on prothrombin time (PT) and partial thromboplastin time (PTT), elevated alpha fetoprotein, anemia, and acidosis at 62.5%, 37.5%, 31.3%, and 31.3%, respectively." (PMID 39311361, 2024). "In fetal anemia, elevated AFP levels are due to the activation of hepatocytes in hepatic hematopoiesis, leading to its increased production and leakage through the swollen placenta into the maternal circulation." (PMID 38256600, 2024). "Before RT, 59 (45.0%) patients had anemia, and the median serum AFP level was 149.3 ng/ml (range: 1.2–515,800.0 ng/ml)." (PMID 36203419, 2022). "Maternal laboratory tests revealed anemia, slightly increased creatinine and uric acid levels, hypoproteinemia, and significantly increased alpha-fetoprotein and hemoglobin-F levels." (PMID 34663239, 2021). "Her laboratory tests, including tumor markers of CA-125, carsinoembryonic antigen (CEA), CA-19-9 and alpha- fetoprotein (AFP) were in normal ranges despite severe anemia as her hemoglobin was 7.1 g/dl." (PMID 27294222, 2016). "Liver damage can give rise to biological signs such as anemia, thrombocytopenia, liver enzyme disorders or increased alpha-fetoprotein levels, which may suggest liver damage." (PMID 40286691, 2025). "Abnormal laboratory parameters include: decreased transferrin; ceruloplasmin; increased ferritin (non-specific, > 800 ng/mL); mixed hyperbilirubinaemia; low aminotransferases; low factors V and VII (< 10% of normal); thrombocytopenia, anaemia and increased alpha-fetoprotein (> 200 ng/mL)." (PMID 21092086, 2010). "During the treatment, he presented seizures, anaemia and febrile neutropenia; the poor clinical response was observed in imaging studies (hepatic metastasis, increased dimensions of brain metastasis with perilesional haemorrhage) and in the tumour markers (AFP 3.73UI/L, HCG 214UI/L and LDH 734UI/L)." (PMID 30792805, 2018). "The patient initially presented with a large pelvic mass, elevated alpha-fetoprotein(AFP) and human chorionic gonadotropin (β-HCG), anemia, and thrombocytopenia." (PMID 41568380, 2025). "This patient was a 19-month-old female who presented with an abdominal mass and laboratory findings significant for anemia, thrombocytosis, elevated lactate dehydrogenase (LDH), direct hyperbilirubinemia, and alpha-fetoprotein (AFP) elevation." (PMID 40755645, 2025). "While alpha-fetoprotein (AFP) and C-reactive protein (CRP) are amongst the most studied ones, the prognostic role of anaemia, a condition often found in cancer patients, is less clear." (PMID 38848660, 2024). "Higher concentrations of CEA, AFP, CA 19-9 were detected in patients with CRC and detectable anemia." (PMID 35611243, 2022).